ANGPTL3 (angiopoietin like 3)
Diseases named in the same sentence as ANGPTL3 in open-access papers (continued):
Sharing a sentence is not in itself a finding about the gene and the disease.
tumor (16 papers, 2015 to 2026). "ANGPTL3 has been reported to be associated with tumoral development and progression." (PMID 25644496, 2015). "In mouse tumor models with increased ANGPTL3, anti-ANGPTL3 therapy significantly reduced tumor growth and synergistically enhanced anti-PD1 therapeutic efficacy." (PMID 41627888, 2026). "METTL3 targets ANGPTL3 and downregulates its expression, which is conducive to tumor growth, proliferation, migration, and invasion." (PMID 39678510, 2024). "CCK-8 assays presented that STAD cells viability was weakened in response to attenuation of METTL3 levels, while ANGPTL3 small interfering RNA partially increased the viability of tumor cells depleted by METTL3 silencing." (PMID 37344779, 2023). "And another important result of this study is to determine the causal connections among ANGPTL3 mRNA m6A levels and METTL3 expression and STAD tumor progression using bioinformatics analysis and comprehensive experiments." (PMID 37344779, 2023). "Normal tissues expressed ANGPTL1 and ANGPTL3, whereas tumor tissues expressed median and low levels." (PMID 35692877, 2022). "In contrast, the DNA methylation levels of ANGPTL2, ANGPTL7, and ANGPTL8 were significantly positively correlated with tumor grade, and the DNA methylation levels of ANGPTL3, ANGPTL5, and ANGPTL7 were significantly negatively correlated with age." (PMID 35692877, 2022). "Overall, our results confirmed that overexpression of ANGPTL3 was related to the malignancy and good prognosis of RCC patients, and ANGPTL3 upregulation inhibited the tumor proliferation and metastasis via the Wnt/β-catenin pathway." (PMID 34484467, 2021). "To screen the possible functional regulator involved in RCC progression, we searched “GEPIA” (A online tool analyzing TCGA datasets), finding that the expression of ANGPTL3 was distinctly decreased in RCC specimens compared with non-tumor renal specimens." (PMID 34484467, 2021). "Then, we further explored the tumor-related functions and molecular mechanisms of ANGPTL3 in RCC progression." (PMID 34484467, 2021). "ANGPTL3 is a secreted protein, and we found that serum human ANGPTL3 levels was higher in tumour-bearing mice than in non-tumour-bearing mice, indicating that human ANGPTL3 was secreted from the xenograft." (PMID 30033448, 2018). "In patients with T3/T4 tumors, the overall survival rate with an ANGPTL3-positive tumor was significantly (P < 0.05) lower than that of ANGPTL3-negative cases." (PMID 25644496, 2015). "We assessed the effect of ANGPTL3 on tumoral growth in vivo by evaluating to target tumor xenografts in nude mice." (PMID 25644496, 2015). "Hence, ANGPTL3 contributes to higher circulating beta‐lipoproteins levels, which are available for tumor uptake." (PMID 39888285, 2025). "Thus, in two distinct models (RCC and HCC), evidence supports that ANGPTL3 functions as a tumor suppressor, modulating sorafenib-mediated cellular functions." (PMID 39708716, 2025). "One explanation could be that circulating lipids are taken up by tumor cells, inducing an upregulation of the hepatic secretion of ANGPTL3 to maintain a preset cholesterolemia." (PMID 38414008, 2024). "Alternatively, increased levels of ANGPTL3 in HGSOC could reflect local production by the tumor itself." (PMID 38414008, 2024). "In such context, ANGPTL3 may be secreted in the tumor microenvironment to mediate pro-angiogenic and pro-metastatic functions, as noted in other cancers." (PMID 38414008, 2024). "In conclusion, ANGPTL3 silencing may serve as a tumor suppressor in CC through integrin αvβ3, which provides a potentially novel therapeutic target for patients with CC." (PMID 35038961, 2022). "Our study demonstrates that ANGPTL3 can exert tumor-promoting effects in CC cells." (PMID 35038961, 2022). "Overall, our findings suggested that ANGPTL3 served as a tumor promotor in RCC." (PMID 34484467, 2021). "In the past years, many studies have revealed the functions of ANGPTL3 in tumor progression." (PMID 34484467, 2021).
tumor (continued). "Sorafenib therapy provided limited benefits for the overall progression-free survival (PFS) of RCC patients, while patients with high ANGPTL3 expression levels in their tumours had a more significant improvement in PFS after receiving sorafenib than those in the control group did." (PMID 30033448, 2018). "As ANGPTL3 is functionally involved in sorafenib response in RCC cells, we further evaluated whether the expression of ANGPTL3 in tumour tissues was associated with the response to sorafenib therapy." (PMID 30033448, 2018). "The ANGPTL3 expression level was correlated closely (P < 0.05) with tumoral size." (PMID 25644496, 2015). "Interestingly, these findings may be reversed by ANGPTL3 inhibition, while ANGPTL3 downregulation may suppress tumor growth and liver metastasis." (PMID 39057711, 2024). "A study demonstrated that ANGPTL3 was highly expressed in oral squamous cell carcinoma (OSCC), where its overexpression promoted tumor growth both in vitro and in vivo via activation of the ERK pathway." (PMID 39708716, 2025). "ANGPTL3, ANGPTL4, ANGPTL5, ANGPTL7, and ANGPTL8 were significantly hypermethylated in tumor tissues." (PMID 35692877, 2022). "We found that ANGPTL1, ANGPTL3, ANGPTL4, ANGPTL6, and ANGPTL7 were differentially expressed between tumor and normal tissues." (PMID 35692877, 2022). "The location of tumor lesion also affected the expression level of ANGPTL1 (P = .0030), ANGPTL2 (P = .0014), ANGPTL3 (P = .0100), and ANGPTL4 (P = .0350) according to K‐W test." (PMID 32410376, 2020). "The limited number of individuals belonging to tumor stages I, II and IV (n = 3, n = 3 and n = 4, respectively) resulted in unequal group sizes and lack of statistical power in group comparisons, which did not permit to study ANGPTL3 and other analytes changes through the different stages." (PMID 38414008, 2024). "However, the different xenografts on the left and the right sides of the same mouse showed different response to sorafenib under the same blood ANGPTL3 concentration, suggesting that the ANGPTL3 in the bloodstream may not be the main factor influencing the response of tumour cells to sorafenib." (PMID 30033448, 2018).
metabolic disease (9 papers, 2018 to 2025). A congenital disorder (due to inherited enzyme abnormality) or acquired (due to failure of a metabolically important organ) disorder resulting from an abnormal metabolic process. "Among these studies, several groups have demonstrated that Angptl3 and 8 serve as important lipid metabolism factors closely associated with metabolic disease." (PMID 31380419, 2019). "These hepatic changes were accompanied by a marked increase in plasma levels of angiopoietin-like 3 (ANGPTL3), a key biomarker associated with metabolic disorders and lipid dysregulation." (PMID 40243850, 2025). "In addition, lipoprotein disorders in which LDL-C concentrations are genetically reduced have been reported, and among them, patients with mutations in the ANGPTL3 and PCSK9 genes are asymptomatic." (PMID 33255270, 2020). "Angptl3 gene expression and ANGPTL3 plasma levels may show marked changes in some metabolic disorders in humans or experimental manipulations in rodents which are characterized by marked elevation of the level of plasma triglycerides." (PMID 29752428, 2019). "Collectively, these findings reveal a novel miR-181d–ANGPTL3 axis that has a vital role in regulating lipid metabolism, and they suggest a potential role for miR-181d in therapy targeting dysregulated lipid metabolism in metabolic diseases." (PMID 31413305, 2019).
infection (2 papers, 2021 to 2025). The state of being infected such as from the introduction of a foreign agent such as serum, vaccine, antigenic substance or organism. "Only ANGPTL-3 mRNA was down-regulated during early infection in vitro, although both ANGPTLs were increased later." (PMID 34360721, 2021). "Compared to mock-infected cells, ANGPTL-3 was down-regulated almost by half in early infection, while ANGPTL-4 remained unchanged." (PMID 34360721, 2021). "At the same time, we determined ANGPTL-3 and ANGPTL-4 gene expression in mRNA samples isolated from sixteen day-long infections of permissive hepatoma cells with HCV-3a." (PMID 34360721, 2021). "Furthermore, high VRL was a significant predictor for ANGPTL-3 and ANGPTL-4 levels after treatment, but not during infection, as would have been expected." (PMID 34360721, 2021).
genetic disorder (1 paper, 2025). "Familial Combined Hypolipidemia (FHBL2) is a genetic disorder caused by loss-of-function mutations in the Angiopoietin-like 3 (ANGPTL3) gene." (PMID 41291732, 2025).
ANGPTL3 also shares sentences with these, for which no sentence is quoted: colorectal cancer (3 papers); nonalcoholic fatty liver disease (3); familial partial lipodystrophy (2); leukemia (2); rheumatic disorder (2); serous carcinoma of the ovary (2); serous ovarian carcinoma (2); Stroke (2); systemic sclerosis (2); acute coronary syndrome (1); Anderson disease (1); anemia (1); aneurysm (1); antibody deficiency against (1); Arthritis (1); autoimmune hepatitis (1); bronchopulmonary dysplasia (1); cerebral aneurysms (1); cholestasis (1); cholesterol ester storage disease (1); congestive heart failure (1); deficiencies (1); Dengue hemorrhagic fever (1); dilated cardiomyopathy (1); familial hypobetalipoproteinemia 1 (1); Fanconi anemia (1); gastric tumor (1); Glomerular sclerosis (1); head and neck cancer (1); heart disease (1).
A further 25 diseases each share a sentence with ANGPTL3 in 1 paper.